EHHADH (enoyl-CoA hydratase and 3-hydroxyacyl CoA dehydrogenase)
Description:
Peroxisomal trifunctional enzyme possessing 2-enoyl-CoA hydratase, 3-hydroxyacyl-CoA dehydrogenase, and delta 3, delta 2-enoyl-CoA isomerase activities. Catalyzes two of the four reactions of the long chain fatty acids peroxisomal beta-oxidation pathway (By similarity). Can also use branched-chain fatty acids such as 2-methyl-2E-butenoyl-CoA as a substrate, which is hydrated into (2S,3S)-3-hydroxy-2-methylbutanoyl-CoA (By similarity). Optimal isomerase for 2,5 double bonds into 3,5 form isomerization in a range of enoyl-CoA species (Probable). Also able to isomerize both 3-cis and 3-trans double bonds into the 2-trans form in a range of enoyl-CoA species (By similarity). With HSD17B4, catalyzes the hydration of trans-2-enoyl-CoA and the dehydrogenation of 3-hydroxyacyl-CoA, but with opposite chiral specificity. Regulates the amount of medium-chain dicarboxylic fatty acids which are essential regulators of all fatty acid oxidation pathways (By similarity). Also involved in the degradation of long-chain dicarboxylic acids through peroxisomal beta-oxidation.
Synonyms: PBFE; MFE1; ECHD; FRTS3; L-PBE; LBFP
Tractability: PROTAC: ubiquitination databases record sites on it; its protein half-life has been measured.
Gene: Protein-coding gene on chromosome 3 (185,190,624 to 185,281,990, reverse strand). Ensembl gene ENSG00000113790.
Subcellular location: Peroxisome
Pathways (Reactome):
Metabolism: Beta-oxidation of very long chain fatty acids
Protein localization: Peroxisomal protein import
Gene Ontology:
Molecular function: (3S)-3-hydroxyacyl-CoA dehydrogenase (NAD+) activity; enoyl-CoA hydratase activity; enzyme binding; long-chain (3S)-3-hydroxyacyl-CoA dehydrogenase (NAD+) activity; protein binding; 3-hydroxyacyl-CoA dehydratase activity; delta(3)-delta(2)-enoyl-CoA isomerase activity; intramolecular oxidoreductase activity, transposing C=C bonds; catalytic activity; NAD+ binding; oxidoreductase activity; oxidoreductase activity, acting on the CH-OH group of donors, NAD or NADP as acceptor
Biological process: fatty acid beta-oxidation; fatty acid beta-oxidation using acyl-CoA oxidase; fatty acid biosynthetic process; fatty acid metabolic process
Cellular component: peroxisome; cytosol; peroxisomal matrix
Genetic constraint (gnomAD): Loss-of-function variants: 37 observed, 55.77 expected, observed/expected ratio (o/e) 0.66, 90% interval 0.51 to 0.87. The upper end of that interval is the gene's LOEUF score, 0.87, which puts it in group 3 of 6, group 1 being the genes least tolerant of losing a copy. Missense variants: 794 observed, 843.47 expected, observed/expected ratio (o/e) 0.94, 90% interval 0.89 to 1. Synonymous variants: 295 observed, 320.14 expected, observed/expected ratio (o/e) 0.92, 90% interval 0.84 to 1.01.
Gene-disease validity (ClinGen):
ClinGen rates the evidence that EHHADH causes each of these diseases.
Fanconi renotubular syndrome 3 (autosomal dominant): Limited.
Homologues: Orthologues: chimpanzee EHHADH (99% identical), macaque EHHADH (96% identical), rabbit EHHADH (85% identical), dog EHHADH (84% identical), pig EHHADH (84% identical), mouse Ehhadh (78% identical), rat Ehhadh (78% identical), zebrafish ehhadh (55% identical), tropical clawed frog ehhadh (54% identical), Caenorhabditis elegans ech-9 (20% identical), Caenorhabditis elegans ech-8 (18% identical). Paralogues in human: HADHA (29% identical), HADH (13% identical), CRYL1 (10% identical).
Diseases named in the same sentence as EHHADH in open-access papers:
EHHADH is named in the same sentence as 66 diseases in open-access papers, as found by Europe PMC text mining. Sharing a sentence is not in itself a finding about the gene and the disease. The quoted sentences say what the papers report.
Fanconi syndrome (8 papers, 2018 to 2025). "Recently, an autosomal dominant mutation leading to the renal Fanconi syndrome, or generalized dysfunction of the proximal tubule, has been identified in the peroxisomal enzyme enoyl-CoA hydratase and 3-hydroxyacyl CoA dehydrogenase (EHHADH)." (PMID 35191396, 2022). "EHHADH (associated with the GO term ‘urate transport’) is involved in fatty acid oxidation, the main energy source for kidney tubule cells and EHHADH mutations have been implicated in Fanconi’s syndrome which is characterized by renal proximal tubule dysfunction." (PMID 30719032, 2018). "For example, a mutation adding an MTS to a native peroxisomal-targeting sequence has been reported in enoyl-CoA hydratase and 3-hydroxyacyl CoA dehydrogenase (EHHADH), leading to renal Fanconi syndrome." (PMID 37283036, 2023). "To date, there is only limited evidence for disease associations of DAO (schizophrenia), RFLNA (spondylocarpotarsal synostosis), and EHHADH (Fanconi renotubular syndrome)." (PMID 31533369, 2019). "Compared with the EHHADH-linked Fanconi’s syndrome, the clinical situation of patients carrying those GATM mutations is quite the opposite: The symptoms typically found in Fanconi’s syndrome are rather mild, e.g., vitamin d-resistant rickets is absent or very mild." (PMID 34349672, 2021).
fatty liver disease (6 papers, 2014 to 2025). A reversible condition wherein large vacuoles of triglyceride fat accumulate in liver cells via the process of steatosis. "Thus, EHHADH, a fairly new candidate protein, was identified to be potentially associated with the pathogenesis of fatty liver disease, for its abundant interaction networks with other proteins." (PMID 32586350, 2020). "Taken together, Gm35585 is a hepatic lipid metabolism regulator that activates EHHADH transcription, promoting peroxisomal β-oxidation of LCFAs and ultimately ameliorating diet-induced fatty liver." (PMID 40082671, 2025). "A reduction in EHHADH expression has been observed in mouse models for chronic kidney disease, hyperlipidemia, obesity and fatty liver disease." (PMID 30719032, 2018). "Furthermore, potential important proteins, such as HADHA, ACAT1, EHHADH, were predicted to be essential regulators during the pathogenesis of fatty liver disease." (PMID 32586350, 2020). "Collectively, the results suggest that ACSL1, ACSL5, EHHADH, and ACAA1 play an important role in the development of fatty liver disease in dairy goats." (PMID 40723475, 2025). "This heterodimer activates EHHADH transcription to increase peroxisome activity and metabolizes excess LCFA and VLCFA over time, thereby improving HFD-induced fatty liver." (PMID 40082671, 2025). "The results showed that the four genes (ACSL1, ACSL5, EHHADH, and ACAA1) were significantly upregulated in the hepatic tissues of dairy goats with fatty liver." (PMID 40723475, 2025). "Furthermore, this study identified potential important proteins, such as HADHA, ACAT1, and EHHADH, which may be important regulatory factors through modification of acetylation in the development of fatty liver disease in dairy cows and possible therapeutic targets for NAFLD in human beings." (PMID 32586350, 2020). "Furthermore, this study identified potential important proteins, such as HADHA, ACAT1, and EHHADH, which may be important regulatory factors being acetylation level modified in the development of fatty liver disease in dairy cows, potentially being therapeutic targets for NAFLD in human beings." (PMID 32586350, 2020). "Notably, by observing the overlap among these three sub-networks, we found that proteins with downregulated ubiquitination—such as ACSL1, ACSL5, EHHADH, and ACAA1—were transcriptionally upregulated in dairy goats with fatty liver." (PMID 40723475, 2025). "Indeed, we observed significantly elevated gene expression of ACSL1, ACSL5, EHHADH, and ACAA1 in the hepatic tissues of periparturient goats affected by fatty liver disease." (PMID 40723475, 2025). "We speculate that the altered ubiquitination of ACSL1, ACSL5, EHHADH, and ACAA1 contributes to their increased hepatic protein levels and abnormal subcellular localization in dairy goats with fatty liver." (PMID 40723475, 2025).
hepatocellular carcinoma (6 papers, 2019 to 2025). A malignant tumor that arises from hepatocytes. "In particular, in hepatocellular carcinoma, higher EHHADH expression is associated with longer survival, fewer recurrences, and lower pathological stage." (PMID 38304003, 2024). "Some studies have shown that EHHADH is highly expressed in the liver and that it is a key gene involved in the fatty acid metabolism pathway in hepatocellular carcinoma." (PMID 40428310, 2025). "Beyond its differential expression, EHHADH is increasingly recognized for its pathogenetic and/or prognostic significance in cancers such as hepatocellular carcinoma, osteosarcoma, colorectal carcinoma, and pituitary adenoma." (PMID 38304003, 2024).
aortic valve disease (3 papers, 2016 to 2022). "For example, FABP3 and EHHADH were up-regulated in the left atria of mitral regurgitation patients compared to in patients with aortic valve disease and normal controls." (PMID 35055737, 2022). "The expressions of ACADM, FABP3, ECH1, ACAA2, EHHADH and CPT1A in the left atria were significantly up-regulated in the MR patients with heart failure compared to patients with aortic valve disease and heart failure and normal controls." (PMID 27250500, 2016). "Notably, only ACADM, FABP3, ECH1, ACAA2, EHHADH, CPT1A and PLTP of the PPAR signaling pathway were differentially expressed in the left atria of MR patients compared to patients with aortic valve disease and normal controls." (PMID 27250500, 2016). "Notably, seven genes (ACADM, FABP3, ECH1, ACAA2, EHHADH, CPT1A and PLTP) of the PPAR signaling pathway were differentially expressed in the left atria of MR patients compared to patients with aortic valve disease and normal controls." (PMID 27250500, 2016). "Notably, only ACADM, FABP3, ECH1, ACAA2, EHHADH, CPT1A and PLTP of the PPAR pathway were significantly differentially expressed in the MR patients compared to patients with aortic valve disease and normal controls." (PMID 27250500, 2016).
bladder cancer (3 papers, 2021 to 2024). "A recent study found that EHHADH depletion restrained proliferation, invasion, and migration of cancer cells, and facilitated the sensitivity of bladder cancer (BC) cells to cisplatin in vitro." (PMID 38213102, 2024). "EHHADH can promote cisplatin resistance in bladder cancer cells." (PMID 35069712, 2022). "Among the BLCA cohort in TCGA, we found that gene expression of EHHADH was somewhat higher in bladder cancer specimens compared with adjacent noncancerous tissues (P = 0.067)." (PMID 33430801, 2021).
lymphoid cancer (3 papers, 2023 to 2025). "Three genes, INTU (p-value 0.004), PEX7 (p-value 0.02), and EHHADH (p-value 0.02) were associated with lymphoid cancers after multiple testing correction for 6 genes with ExAC controls." (PMID 37379307, 2023). "SPRR1B may be oncogenic in epithelial cells, while EHHADH has also been linked with non-lymphoid cancers." (PMID 38143765, 2023). "A splice acceptor deletion NM_001966.4:c.594_595del (rs781090244) in EHHADH was observed in two unrelated familial lymphoid cancer cases, one diagnosed with CLL at the age of 34 and one with DLBCL at the age of 34." (PMID 37379307, 2023). "Four genes, INTU (p-value 0.005), ASXL1 (p-value 0.009), EHHADH (p-value 0.03) and PEX7 (p-value 0.02), were associated with lymphoid cancer after multiple testing correction for 7 genes when GnomAD exomes were used as controls." (PMID 37379307, 2023). "Since affected family members of both cases did not have the same variant in ASXL1 or EHHADH, it is plausible that other factors contribute to familial lymphoid cancer in these families." (PMID 37379307, 2023). "The genes EHHADH, INTU, PEX7, and ASXL1 were found to have a significantly higher burden of deleterious variants in cases than controls; variants in these genes may contribute to risk of lymphoid cancers in specific individuals." (PMID 37379307, 2023). "Variants in EHHADH and AXSL1 did not segregate with lymphoid cancer in the families studied, which implies that the variants do not play a role in all affected members of these families, it does not rule out their making a contribution to cancer predisposition in the original case." (PMID 37379307, 2023).
atherosclerosis (2 papers, 2024 to 2025). A disease characterized by the build-up of fatty material and calcium deposition in the arterial wall resulting in partial or complete occlusion of the arterial lumen. "The down-regulation of EHHADH expression has been reported to decrease the rate of very low-density lipoprotein (VLDL) transport, and accumulation of high levels of VLDL increases the risk of atherosclerosis and cardiovascular disease." (PMID 40422873, 2025).
diabetic kidney disease (2 papers, 2021 to 2024). Progressive kidney disorder caused by vascular damage to the glomerular capillaries, in patients with diabetes mellitus. "In the present study, we showed that the loss of EHHADH aggravated renal tubular injury in mice with diabetic kidney disease and resulted in a loss of peroxisomes in renal tubular epithelial cells (RTECs) as a novel pexophagy modulator." (PMID 38879653, 2024). "Here, we found that endogenous EHHADH levels were strongly correlated with the progression and severity of diabetic nephropathy in T2D patients." (PMID 38879653, 2024). "Peroxisomal l-bifunctional enzyme (EHHADH) plays a role in the classic peroxisomal fatty acid β-oxidation pathway; however, the relationship between EHHADH expression and diabetic kidney disease has not been well understood." (PMID 38879653, 2024). "The role of EHHADH in the peroxisomal FAO pathway has been well-characterized, but it remains poorly understood the implication of EHHADH for diabetic kidney disease." (PMID 38879653, 2024).
melanoma (2 papers, 2023 to 2025). A malignant, usually aggressive tumor composed of atypical, neoplastic melanocytes. "EHHADH, essential for the peroxisomal beta-oxidation process, has shown increased mRNA expression in some melanoma cell lines." (PMID 37844995, 2023).
ovarian carcinoma (2 papers, 2021 to 2024). A malignant neoplasm originating from the surface ovarian epithelium. "Enoyl-CoA hydratase and 3-hydroxyacyl CoA dehydrogenase (EHHADH) influences lipid metabolism and aerobic glycolysis in ovarian cancer." (PMID 38783226, 2024).
renal carcinoma (2 papers, 2019 to 2025). A carcinoma arising from the epithelium of the renal parenchyma or the renal pelvis. "CLCN5 can significantly reduce lipid storage, and EHHADH may be a downstream of CLCN5 in renal cancer cells." (PMID 40765554, 2025). "Bioinformatics and cell experiments had demonstrated that EHHADH might be a unique downstream and mediated lipid degradation of CLCN5 in renal cancer cells." (PMID 40765554, 2025). "In addition, immunohistochemistry staining in The Human Protein Atlas database showed that the expression of EHHADH, ACADM and AGXT2 proteins were also significantly lower in renal carcinoma compared to normal kidney." (PMID 31839812, 2019).
amyloidosis (1 paper, 2021). A disorder characterized by the localized or diffuse accumulation of amyloid protein in various anatomic sites. "Specifically, the proteins involved in amyloidosis, including optineurin (OPTN), ras‐related protein Rab‐21 (Rab21), dynamin 1 (DNM1), peroxisomal bifunctional enzyme (EHHADH), fermitin family homolog 2 (FERMT2), E3 ubiquitin‐protein ligase UBR1 were increased in T2DM‐MCI compared with T2DM‐nMCI." (PMID 34528736, 2021).
clear cell renal cell carcinoma (1 paper, 2025). "Therefore, the present research has unveiled a crucial regulatory mechanism for lipid metabolism of CLCN5/EHHADH signal in clear cell renal cell carcinoma." (PMID 40765554, 2025).
cleft lip (1 paper, 2025). Congenital defect in the upper lip where the maxillary prominence fails to merge with the merged medial nasal prominences. "We report two novel mutations associated with nonsyndromic cleft lip in adjacent genes EHHADH and MASP1." (PMID 41378467, 2025). "Based on these findings, we propose a novel compound inheritance model for nonsyndromic cleft lip involving the interaction between metabolic processes regulated by EHHADH and immune signaling pathways controlled by MASP1." (PMID 41378467, 2025).
colorectal cancer (1 paper, 2024). A primary or metastatic malignant neoplasm that affects the colon or rectum.
cone-rod dystrophy (1 paper, 2025). Inherited retinal dystrophies that belong to the group of pigmentary retinopathies. "The database analysis confirmed the presence of EHHADH variants in patients with complex phenotypes including abnormalities of the eye (cone/cone-rod dystrophy), musculoskeletal system (microcephaly), nervous system (epileptic encephalopathy), and other features (microcephaly, central hypotonia)." (PMID 41378467, 2025).
endometriosis (1 paper, 2025). The growth of functional endometrial tissue in anatomic sites outside the uterine body. "There has been limited research on the roles of ACSL5, PLA2G4A, EHHADH, GPAM, PLA2G15, SULT2A1, and ACSL3 in endometriosis, highlighting the necessity for further investigation to elucidate their contributions to its pathogenesis." (PMID 40527850, 2025).
gout (1 paper, 2018). A condition characterized by painful swelling of the joints, which is caused by deposition of urate crystals. "The serum urate-raising and gout risk allele rs7188445_G associates with increased MAFTRR expression and lowered EHHADH expression." (PMID 30719032, 2018).
Hyperglycemia (1 paper, 2024). An increased concentration of glucose in the blood. "We have identified that downregulation of EHHADH can lead to peroxisomal deficiency, which in turn increases the susceptibility to tubular injury and fibrosis under hyperglycemia." (PMID 38879653, 2024).
hyperthyroidism (1 paper, 2022). Overactivity of the thyroid gland resulting in overproduction of thyroid hormone and increased metabolic rate. "Our results suggest that EEP attenuates hyperthyroidism-induced oxidative stress via the PPAR and AMPK pathways, with the main targets of action being by influencing the expression of FABP and HMGCR at the protein level and by affecting the expression of EHHADH, HMGCR, and SLC27A2 at the mRNA level." (PMID 36613632, 2022).
kidney failure (1 paper, 2022). An acute or chronic condition that is characterized by the inability of the kidneys to adequately filter the blood. "FRTS3 is the prototype of RFS characterized by no kidney failure and the autosomal dominant inheritance of heterozygous missense mutation in the EHHADH gene." (PMID 36431026, 2022).
kidney tumor (1 paper, 2024). "Representative immunohistochemistry data from The Human Protein Atlas consistently demonstrated that kidney tumor samples expressed lower levels of EHHADH compared to healthy kidney samples." (PMID 38304003, 2024). "In summary, analysis of several databases revealed that EHHADH mRNA and protein expression is lower in kidney tumor samples than in control samples, and that reduced EHHADH expression correlates with poorer survival." (PMID 38304003, 2024).
liver cancer (1 paper, 2024). An epithelial or non-epithelial malignant neoplasm that arises from the liver. "The results illustrated a clear trend of downregulation in the protein levels of EHHADH in the majority of liver cancer samples." (PMID 38637116, 2024). "Finally, we complemented the immunohistochemical experiments of EHHADH with a tissue microarray of liver cancer." (PMID 38637116, 2024).
liver disease (1 paper, 2025). "Activation of EHHADH promotes the oxidation of long-chain fatty acids (LCFAs), and the increased levels of hepatic LCFAs contribute to metabolic-dysfunction-associated steatotic liver disease." (PMID 40082671, 2025).